FAS (Fas cell surface death receptor)
Diseases named in the same sentence as FAS in open-access papers (continued):
Sharing a sentence is not in itself a finding about the gene and the disease.
myelodysplastic syndrome (7 papers, 2016 to 2025). A clonal hematopoietic disorder characterized by dysplasia and ineffective hematopoiesis in one or more of the hematopoietic cell lines. "Here again no recurrent genetic alterations have been reported, but leukaemic blasts were shown to decrease or lose FAS expression during transformation from myelodysplastic syndrome to AML and this correlates with increased methylation of the FAS promoter." (PMID 29017180, 2017).
pulmonary fibrosis (7 papers, 2020 to 2024). Chronic progressive interstitial lung disorder characterized by the replacement of the lung tissue by connective tissue, leading to progressive dyspnea, respiratory failure, or right heart failure. "Interestingly, resistance from FAS-induced apoptosis was recently implicated as a mechanism that contributed to persistent lung fibrosis in aged mice, and inhibition of this apoptotic pathway in fibroblasts contributed to their pathogenic activation and persistence in the lung after injury." (PMID 35167499, 2022). "The functional role of FAS in the development of pulmonary fibrosis is evident from studies showing that agonistic FAS antibody (which mimics crosslinking between FASL and FAS) resulted in the apoptosis of epithelial cells, leading to fibrosis." (PMID 36139863, 2022). "Taken together, these findings demonstrate the importance of FAS in epithelial cell apoptosis and resistance to FAS-induced apoptosis in myofibroblasts in the pathogenesis of lung fibrosis." (PMID 36139863, 2022). "Additionally, some studies have shown that loss of MMP-12 can protect mice from smoke-induced lung disease and FAS-induced pulmonary fibrosis." (PMID 38355586, 2024).
renal carcinoma (7 papers, 2006 to 2022). A carcinoma arising from the epithelium of the renal parenchyma or the renal pelvis. "Previous studies reported that mTOR pathway, GSK3 pathway, AKT pathway, EIF4 pathway, MET pathway, NFAT pathway, and FAS pathway acted as essential factors in the development of renal cancer and that CHREBP2 pathway, EDG1 pathway, and CTCF pathway were also cancer-related pathways." (PMID 33102202, 2020). "All three genes, CFLAR, FAS, and FASLG, were significantly higher expressed in ccRCC compared with the other two renal cancer types." (PMID 31097685, 2019). "Moreover, analysis of public data on the expression levels of c-FLIP (CFLAR), CD95 (FAS/TNFRSF6), and CD95L (FASLG) revealed significantly higher expression of these three genes in ccRCC compared with other renal cancers." (PMID 31097685, 2019).
type 1 diabetes (7 papers, 2014 to 2026). "One of the KEGG pathways that showed enrichment was “Type I diabetes mellitus” and the analyzed module contains two genes from this pathway—FAS and IL1B." (PMID 27257970, 2016). "Regarding the 16 up-regulated genes, S100A3, AXL, IL12A, XPC and FAS identified GO terms such as positive regulation of natural killer cell activation, response to UV-B, African trypanosomiasis, allograft rejection and Type I diabetes mellitus." (PMID 24756038, 2014).
acute myeloid leukemia (6 papers, 2016 to 2022). Acute myeloid leukemia (AML) is a group of neoplasms arising from precursor cells committed to the myeloid cell-line differentiation. "Similarly, a previous hypothetical association between FAS-670 A/G SNP and acute myeloid leukemia (AML) has been rejected." (PMID 35059842, 2022).
breast tumors (6 papers, 2013 to 2021). "Further experiments are needed to test the activity of FAS in breast-tumor cells after Resv exposure." (PMID 32149115, 2020). "Breast tumor cells frequently down-regulate FAS and/or up-regulate FASL expression." (PMID 23326385, 2013). "Given that irradiation induced FAS and FASL in breast tumors lacking miR-21, we evaluated the activation of the caspase cascade." (PMID 33672628, 2021).
dyslipidemia (6 papers, 2013 to 2025). "Western diet (e.g. high-fat diet, HFD) is one of the critical factors of HCE development, as it alters lipogenesis-linked enzyme expression (e.g. liver X receptor α/β, LXRa/β; acetyl-CoA carboxylase, ACC; and fatty acid synthase, FAS), consequently causing dyslipidemia." (PMID 41189665, 2025). "To identify the molecular mechanisms underlying the ability of HMC to improve dyslipidemia, we investigated the expression of AMPK, the lipogenesis-related transcription factors PPARα and SREBP-1c, and the lipogenesis-related enzyme FAS, in the liver." (PMID 35565920, 2022). "Such contextual synthetic inhibition of FAS by metformin may partly explain the drug’s demonstrated ability to decelerate growth in some cancers of the diabetic patient or patients with metabolic syndrome." (PMID 24482631, 2014). "HMC also significantly stimulated AMPKThr172 and PPARα in the liver, and ameliorated dyslipidemia by inhibiting SREBP-1c and FAS." (PMID 35565920, 2022).
Huntington disease (6 papers, 2012 to 2026). Huntington disease (HD) is a rare neurodegenerative disorder of the central nervous system characterized by unwanted choreatic movements, behavioral and psychiatric disturbances and dementia. "Finally, the four most abundant pathways of the oxidative-reductive transcripts were the FAS signaling pathway, apoptosis signaling pathway, Huntington’s disease, and CCKR signaling map." (PMID 37351104, 2023). "Indeed, three different pathways resulted as being over-represented, namely, the FAS signaling pathway, Huntington disease and T cell activation pathways, that therefore seem involved in tumor relapse, differently from GBM of new diagnosis." (PMID 35216175, 2022).
thyroid cancer (6 papers, 2014 to 2024). "Additional mechanism studies including FAS and FASLG are needed to define the risk of thyroid cancer in AT/AU patients." (PMID 29950587, 2018).
acute liver failure (5 papers, 2016 to 2025). Rapid deterioration of liver function causing encephalopathy and coagulopathy. "Hepatocytes are very sensitive to FAS-induced apoptosis and administration of CD95-Ab results in rapid death in mice due to fulminant hemorrhagic hepatitis, mimicking acute liver failure in humans." (PMID 29580866, 2018).
African trypanosomiasis (5 papers, 2014 to 2024). "More so, three unique Muturu candidate genes, namely FAS, IDO2, and PLCB1, are part of the candidate African trypanosomiasis KEGG pathway (BTA05143) revealed following functional annotation terms by DAVID bioinformatic tool." (PMID 31231417, 2019).
astrocytoma (5 papers, 2015 to 2025). "Interestingly, one study showed that caspase-1 mediates FAS-induced cell death in astrocytoma cells." (PMID 40512405, 2025).
atherosclerosis (5 papers, 2020 to 2024). A disease characterized by the build-up of fatty material and calcium deposition in the arterial wall resulting in partial or complete occlusion of the arterial lumen.
brain tumor (5 papers, 2015 to 2022). "The FAS-FAS ligand system in human brain tumors was shown to be involved not only in apoptotic processes, but also in the promotion of angiogenic and proinflammatory responses." (PMID 33987093, 2021). "Overexpression of FAS/CD95 receptor and its cognate FAS ligand (FASL) are known to develop resistant in brain tumors toward etoposide treatment." (PMID 25883904, 2015).
colitis (5 papers, 2015 to 2024). Inflammation of the colon. "In this experiment, DSS-induced colitis model mice were used to evaluate the anti-inflammatory effect of FAS." (PMID 39274922, 2024). "The AS and FAS treatments significantly ameliorated DSS-induced weight loss, diarrhea, and shortened colon in mice, indicating that AS and FAS have a therapeutic effect on colitis in mice." (PMID 39274922, 2024). "Therefore, FAS has the potential to regulate the balance of the intestinal microbiota to alleviate the symptoms of colitis." (PMID 39274922, 2024). "In the present study, FAS significantly increased the levels of CAT, T-AOC, and T-SOD, and inhibited the levels of MDA, MPO, and ALT in DSS-induced colitis mice." (PMID 39274922, 2024). "Overall, our results implicate that BID importantly regulates neutrophil death in the context of FASL > FAS and DSS colitis and that through this anti-inflammatory function BID may counteract development of inflammatory diseases such as IBD." (PMID 29495595, 2018).
Ewing sarcoma (5 papers, 2007 to 2021). A small round cell tumor that lacks morphologic, immunohistochemical, and electron microscopic evidence of neuroectodermal differentiation. "The induction of apoptosis can be impeded by miR-181c-5p owing to its potentiality to target Fas cell surface death receptor (FAS) in Ewing’s sarcoma." (PMID 33799952, 2021). "Here, we show that miRNAs play an important function in the down-regulation of FAS expression in Ewing’s sarcoma (ES) cells." (PMID 29563856, 2018). "Also, when we examined whether microRNA that binds to the FAS mRNA 3′-UTR is elevated in a microRNA array, we found that miR-181c was elevated in all five Ewing sarcoma cell lines." (PMID 29563856, 2018). "Because IER3 is a modulator of apoptosis through TNFalpha or FAS-signaling, the balance between its repression (through MYC, E2F2 and E2F5 that are EWS-FLI1 induced and therefore disease specific) and activation (through NFkB) may be of particular interest in Ewing sarcoma." (PMID 23935076, 2013).
lymphoproliferative disorder (5 papers, 2011 to 2025). "About 63.2% of PCMZL/lymphoproliferative disorder carry dominant-negative mutations involving the death domain of the apoptosis-regulating FAS/CD95 protein." (PMID 36460764, 2023). "The same group later report that mice develop a lymphoproliferative disorder that had features resemblant of FAS-deficient Faslpr mice, consistent with a loss of CASPASE8-dependent FAS-triggered cell death." (PMID 41503140, 2025).
myocardial infarction (5 papers, 2016 to 2023). Gross necrosis of the myocardium, as a result of interruption of the blood supply to the area, as in coronary thrombosis. "For example, a genetic variation in the FAS gene was associated with an increased occurrence of myocardial infarction in Japanese subjects." (PMID 28450971, 2017). "Our study indicates that miR-21 attenuates FAS-mediated cardiomyocyte apoptosis by regulating HIPK3 expression, which could eventually have important clinical implications for patients with acute myocardial infarction." (PMID 37581369, 2023).
Parkinson disease (5 papers, 2012 to 2026). A progressive degenerative disorder of the central nervous system characterized by loss of dopamine producing neurons in the substantia nigra and the presence of Lewy bodies in the substantia nigra and locus coeruleus. "Increased effector/memory T cells (Tem), defined as CD45RO+ and FAS+ CD4+ T cells and decreased CD31+ and α4β7+ CD4+ T cells were associated with progressive Unified Parkinson’s Disease Rating Scale III scores." (PMID 23054369, 2012). "In accordance with previous findings, these 83 cancer related proteins confirmed the overrepresentation of the FAS and the FGF signaling, the CCKR signaling map, the Parkinson’s disease, the EGF receptor signaling, the integrin signaling, and the gonadotropin-releasing hormone receptor pathways." (PMID 32183175, 2020).
rheumatoid arthritis (5 papers, 2016 to 2023). A chronic, systemic autoimmune disorder characterized by inflammation in the synovial membranes and articular surfaces. "Studies have shown that FAS-670's GG genotype can cause a decrease in FAS expression in synovial and T cells from patients with rheumatoid arthritis." (PMID 36934132, 2023).
squamous carcinoma (5 papers, 2013 to 2025). "Both penile tumors (squamous cell carcinoma) exhibited mutations in BRCA1 and FAS, as well as ARID1A, CHEK2, BRCA2, and were Human Papillomavirus (HPV) positive." (PMID 41395625, 2025). "FAS expression was studied in 60 squamous cell carcinomas of the oral cavity." (PMID 23894399, 2013). "Owing to these results, the present study aimed to correlate FAS/FASL tumor expression with clinical variables, tumor histology and prognosis of squamous cell carcinoma of the oral cavity." (PMID 23894399, 2013).
anemia (4 papers, 2016 to 2023). A reduction in the number of red blood cells, the amount of hemoglobin, and/or the volume of packed red blood cells. "Postpartum women who had children carriers of FAS and FAD had a higher frequency of urinary tract infection (65.2%) and moderate anemia (23.8%)." (PMID 36522644, 2022).
bladder urothelial carcinoma (4 papers, 2012 to 2024). "Loss of FAS expression was found to significantly correlate with worse prognosis in patients with urothelial carcinomas of the bladder, ureter, and renal pelvis." (PMID 38791085, 2024). "The aim of this research was to assess the association of death receptors DR4, DR5, and FAS as well as TGF-β1 immunohistochemical expression with the clinicopathological characteristics of urothelial bladder cancer (UBC) and to evaluate their prognostic significance." (PMID 38791085, 2024). "This study indicated that the expression of death receptors DR4, DR5, and FAS in urothelial bladder cancer is significantly decreased in muscle-invasive UBC." (PMID 38791085, 2024).
co-infection (4 papers, 2012 to 2018). "Co-infection of the striatum from wild type mice with three different Cre-Off rAAV combinations (DO + DO, DO + FAS, and FAS + FAS) also resulted in expression patterns lacking spatial interference." (PMID 22866029, 2012).
colon adenocarcinoma (4 papers, 2021 to 2024). "In addition, lower expression of PIR plus higher expression of FAS is correlated with the highest survival rate in colon adenocarcinoma dataset derived from Oncomine database." (PMID 38148593, 2024).
graft versus host disease (4 papers, 2016 to 2025). An immune system disorder that occurs after allogeneic hematopoietic stem cell transplant and is a reaction of donor immune cells against host tissues. "Another study reported that a microRNA-based strategy was conducive to improving mouse BM-MSC immunotherapy through the FAS/FASL pathway in graft-versus-host disease, inflammatory bowel disease and other immune and inflammatory diseases." (PMID 37957770, 2023).
head and neck cancer (4 papers, 2013 to 2023). A primary or metastatic malignant neoplasm affecting the head and neck. "Gastman and colleagues reported that the FAS/FASL pathway may participate in the immunosuppression process in head and neck cancer." (PMID 24086353, 2013).
Hypertension (4 papers, 2012 to 2024). The presence of chronic increased pressure in the systemic arterial system. "FAS on 10q24.1 is associated with hypertension, decreased body size, and increased body weight in mice." (PMID 22479346, 2012).
latent infection (4 papers, 2014 to 2025). "The role of FAS in Epstein–Barr virus (EBV) lytic and latent infection has also been explored, showing that FAS plays an important role for the EBV lytic replication." (PMID 35053112, 2022). "Also, consistent with previous analyses using primary CD34+ cells, latent infection of Kasumi-3 cells resulted in their protection from FAS-mediated killing (lane 5)." (PMID 25957098, 2015). "FAS-mediated killing was also inhibited by the pan-caspase inhibitor Z-VAD-FMK (lane 3), and control siRNA itself did not induce cell death in the presence of HCMV latent infection (lane 4)." (PMID 25957098, 2015).
liver diseases (4 papers, 2022 to 2023). "Although we found up-regulation of SREBP–1c and FAS genes, our histopathological study strongly indicated lower severity of hepatic disease in the treatment groups." (PMID 36166461, 2022). "Abnormally increased expressions of FAS and FASL have been documented in inflammatory liver diseases including fibrosis." (PMID 37898449, 2023).
liver failure (4 papers, 2013 to 2024). A liver disease characterized by the liver losing or has lost all of its function. "In line with this, siRNAs were directed against the mRNA of the Fas cell surface death receptor (FAS gene) in an autoimmune hepatitis mouse model, which silenced Fas-expression and consequently protected mice from liver failure and fibrosis." (PMID 38255196, 2024).
nasopharyngeal carcinoma (4 papers, 2013 to 2023). A carcinoma arising from the nasopharyngeal epithelium. "Quercetin also reduced FAS expression levels and inhibited cell proliferation in nasopharyngeal carcinoma cells." (PMID 25971889, 2015).
osteosarcoma (4 papers, 2011 to 2025). A usually aggressive malignant bone-forming mesenchymal neoplasm, predominantly affecting adolescents and young adults. "Supportively, FAS inhibition was reported to suppress osteosarcoma cell invasion and migration via downregulation of the PI3K/Akt signaling pathway." (PMID 40133683, 2025). "Next, we evaluated DNA methylation and gene expression of FAS in two osteosarcoma cell lines, SaOS-2 and LM7." (PMID 37569529, 2023). "Our study indicates that treatment of LM7 osteosarcoma cells with 5-aza resulted in demethylation of the promoter CpG sites and increased FAS protein expression compared with untreated LM7 cells." (PMID 37569529, 2023). "Overall, our results indicate that FAS promoter methylation in the CpG island shore may regulate the expression of FAS, thereby altering the metastatic potential of osteosarcoma patients." (PMID 37569529, 2023). "Based on these results, we have shown preliminary evidence that demethylation of the FAS promoter by 5-aza treatment in LM7 osteosarcoma cells may lead to an improvement in prognosis due to decreased presence of lung metastasis." (PMID 37569529, 2023). "Using one of the largest osteosarcoma cohorts to date, we showed that FAS expression may be used as a prognostic marker for outcome in the primary tumor." (PMID 37569529, 2023). "They evaluated four SNPs in FAS in 123 osteosarcoma cases and 510 controls from the US." (PMID 21437228, 2011). "LM7, a metastatic osteosarcoma cell line, has significantly reduced FAS expression in comparison to its non-metastatic parental cell line, SaOS-2." (PMID 37569529, 2023). "FAS is likely not the only gene with epigenetic dysregulation in osteosarcoma, and further work must be done to comprehensively evaluate the methylome of osteosarcoma patients and integrate it with other genomic platforms for a more comprehensive understanding of osteosarcoma tumor biology." (PMID 37569529, 2023).
primary immunodeficiencies (4 papers, 2019 to 2025). "Interestingly, of the newly identified associations, six include proteins encoded by MMDGs, 2 of which are known to cause primary immunodeficiencies, i.e., Ficolin-3 and FAS." (PMID 35264221, 2022). "Finally, we identified new genetic associations with plasma protein levels of five monogenic Mendelian disease genes including two primary immunodeficiency genes (Ficolin-3 and FAS)." (PMID 35264221, 2022).
psoriasis (4 papers, 2015 to 2025). An autoimmune condition characterized by red, well-delineated plaques with silvery scales that are usually on the extensor surfaces and scalp. "LRIG1 negatively regulates growth factor signaling to regulate epidermal stem cell quiescence; SIK2 modulates cytokine responses during innate immune activation; FAS signaling is essential for inducing key inflammatory cytokines in psoriasis." (PMID 34068434, 2021). "Several psoriasis-related genes were among the associated genes of hsa_skin_088763, including GATA6, SIK2, IL17RD, EGR3, FAS, LRIG1, and PPARGC1A." (PMID 34068434, 2021). "We confirmed the decreased expression of these and FAS (which by gene expression had 9.3- and 1.1-fold changes in the DPCP day 3 and psoriasis transcriptomes, respectively) at the protein level by immunohistochemistry." (PMID 26236467, 2015). "Additionally, studies have shown that other genes such as FAS, BAX, and BCL-2 also exhibit different expression patterns in the skin of psoriasis patients, and these genes are directly involved in the regulation of apoptosis." (PMID 40557155, 2025).